TRIO (trio Rho guanine nucleotide exchange factor)
Diseases named in the same sentence as TRIO in open-access papers (continued):
Sharing a sentence is not in itself a finding about the gene and the disease.
developmental delay (4 papers, 2019 to 2025). "A year later, a deletion mutation partially including TRIO gene has been reported to cause mild ID, developmental delay, behavioral defects, and facial dysmorphism." (PMID 30934641, 2019). "In line with its extensive involvement in brain development, mutations in the TRIO gene have been associated with neurological and neurodevelopment disorders such as intellectual disability (ID), schizophrenia, developmental delay, and autism spectrum disorders (ASDs)." (PMID 30934641, 2019).
myxofibrosarcoma (4 papers, 2020 to 2024). A malignant fibroblastic neoplasm arising from the soft tissue. "Furthermore, ITGA10 can drive tumorigenesis in myxofibrosarcoma by promoting tumor cell survival through the activation of TRIO-RAC-RICTOR-mTOR signaling." (PMID 38017134, 2024). "This study provides evidence that integrin α10 subunit may control growth and metastasis development in myxofibrosarcoma, and targeting integrin α10/TRIO/RICTOR pathway with EHop-016 and INK128 inhibitors could be clinically beneficial for myxofibrosarcoma patients." (PMID 34957097, 2021). "A study analyzed the gene expression profile of 64 cases of primary myxofibrosarcoma and found that patients with high ITGA10 expression had a significantly worse prognosis, revealing that ITGA10 promotes tumor cell survival by activating TRIO/RICTOR signaling." (PMID 33335550, 2020).
sarcoma (4 papers, 2017 to 2024). A usually aggressive malignant neoplasm of the soft tissue or bone. "This broad distribution among different sarcoma types might indicate that TRIO fusions are a secondary event implicated in tumor progression." (PMID 38611033, 2024). "Translocations of the kinase TRIO have been recently detected by NGS approaches in different sarcomas with complex karyotypes, including undifferentiated pleomorphic sarcomas, dedifferentiated liposarcomas, pleomorphic rhabdomyosarcoma and myxofibrosarcoma." (PMID 38611033, 2024). "Genes located in 5p that have been suggested as possible amplicon targets in sarcomas include NKD2, TERT, IRX2, TRIO, AMACR, SKP2 and RICTOR." (PMID 28652867, 2017). "In this report, RNA sequencing of 117 non-translocation-related sarcomas, including 15 MFSs, identified one recurrent TRIO fusion genes with various partners in seven cases including one MFS." (PMID 30018380, 2018).
uveal melanoma (4 papers, 2020 to 2022). A melanoma derived from melanocytes of the uveal tract. "In uveal melanoma cells, the TRIO-RHO/RAC signaling axis lies downstream of oncogenic GNAQ/11 and stimulates YAP, a critical component of the Hippo signaling pathway, which in turn controls cell proliferation 50,69." (PMID 35673577, 2022). "In uveal melanoma, activation of Gαq/11 drives cell proliferation and stimulates the ‘MAPK’ pathway and activates the Hippo pathway through nuclear localization of YAP1 via a TRIO-RHO/RAC signaling circuit." (PMID 34939927, 2021). "Uveal melanomas driven by mutant GNAQ/GNA11 (Gαq proteins) activate FAK through TRIO-RHOA non-canonical Gαq; FAK, in turn, activates YAP, which promotes aberrant uveal melanoma growth." (PMID 35159327, 2022).
malaria (3 papers, 2014 to 2025). Malaria is a serious and sometimes fatal disease caused by a parasite that commonly infects a certain type of mosquito which feeds on humans. "In this study, five salivary proteins – gSG6, gSG1b, long form D7, SG5 and TRIO – were selected as potential candidate biomarkers of exposure to Anopheles infective bites in order to evaluate the risk of malaria transmission." (PMID 25526764, 2014). "TRIO VLPs were similarly immunogenic when combined with an anti-malaria vaccine targeting the L9 epitope of the Plasmodium falciparum circumsporozoite protein." (PMID 39878467, 2025). "To complement the role of anti-sporozoite antibodies, we designed a VLP vaccine targeting TRIO, a salivary protein found in many Anopheles species that are vectors for human malaria parasites, including An." (PMID 39878467, 2025). "However, when used in a malaria challenge mouse model, TRIO VLPs only provided modest protection from infection and did not boost the protection provided by L9 VLPs." (PMID 39878467, 2025). "In addition, genes encoding SG1 family proteins, such as SAG (Saglin), TRIO (triple functional domain protein) and GILT (mosquito gamma-interferon-inducible lysosomal thiol reductase), that are associated with infection by malaria parasites also showed a cyclic profile." (PMID 40164831, 2025).
asthma (2 papers, 2020 to 2023). "Of note, the results from Mendelian randomization were also consistent with the results from the independent Project Viva study—e.g., cg12547959 on TRIO was associated with higher asthma risk and reduced FEV1." (PMID 37679381, 2023). "In addition to these four apoptosis-related genes (TRIO, PEA15, KLRK1, NDUFA13), we also found that the other genes in desensitization-treatment-related module exhibiting distinct degree of correlations to asthma via literature review." (PMID 32948203, 2020).
cervical cancer (2 papers, 2007 to 2022). A primary or metastatic malignant neoplasm involving the cervix. "Thus, upregulation of expression through amplification may be the case for TRIO, ANKH and SKP2 in some neoplasms, including cervical cancer, as indicated by our data." (PMID 17311676, 2007).
glioblastoma (2 papers, 2012 to 2019). The most malignant astrocytic tumor (WHO grade IV). "Upregulation of TRIO expression, often associated with poor patient survival, is found in different tumor types, including urinary bladder, breast, lung soft tissue sarcoma, and glioblastoma." (PMID 31035417, 2019). "Accordingly, TRIO-directed siRNA oligonucleotides suppress glioblastoma cell migration and invasion and also reduce the rate of cell proliferation." (PMID 31035417, 2019).
Hearing impairment (2 papers, 2018 to 2021). A decreased magnitude of the sensory perception of sound. "TRIOBP is a binding protein for TRIO, a guanine nucleotide exchange factor and its mutations are associated with hearing impairment." (PMID 30140277, 2018).
lung carcinoma (2 papers, 2010 to 2024). "There are no definitive reports on the relationship between SDHA and TRIO and lung cancer at present." (PMID 39669196, 2024).
apraxia (1 paper, 2026). Apraxia is a neurological disorder characterized by the inability to perform tasks or movements, despite having the desire and physical ability to perform them. "PRPF8 and TRIO were present in the module previously found enriched for genes linked to childhood apraxia of speech." (PMID 40836029, 2026). "Interestingly, a likely pathogenic missense variant in SPTBN1 has been described in a proband with speech delay, and a missense variant of unknown significance in TRIO in a proband with childhood apraxia of speech." (PMID 40836029, 2026).
aseptic meningitis (1 paper, 2012). Inflammation of the membranes surrounding the brain and spinal cord without a bacterial pathogen. "We expect the regulation of TRIO-RhoA signaling may represent a new therapeutic approach in treating aseptic meningitis and encephalitis induced by Echo30." (PMID 22586486, 2012).
Ataxia (1 paper, 2012). Ataxia refers to impaired coordination of voluntary muscle movement. "TRIO-deficient mice display severe phenotypes, including low survival rate, ataxia and multiple developmental defects of the cerebellum." (PMID 22586486, 2012).
Atrophy (1 paper, 2022). Any weakening or degeneration, especially through lack of use. "More generally, genetic aberrations of many of the differentially methylated genes in our study, i.e., TRIO, NRXN2, SYN2, CACNA1E, DNM1 and RAB11B, have been associated with movement disorders, cognitive and visual impairments and brain abnormalities (e.g., atrophy, white matter apoplasia)." (PMID 35094644, 2022).
Coffin-Siris syndrome (1 paper, 2019). Coffin-Siris syndrome (CSS) is a rare congenital multi-systemic genetic disorder characterized by aplasia or hypoplasia of the distal phalanx or nail of the fifth digit, developmental delay, intellectual disability, coarse facial features, and other variable clinical manifestations. "In particular, proband 19 carried a p.D2155N (c.6463G>A) variant in TRIO, a gene which has been associated with ASD and ID, and proband 18 carried a deletion of five amino acids (c.1029_1043del, p.Ala345_Ala349del) in ARID1A, one of the causal genes for Coffin–Siris syndrome." (PMID 29463886, 2019).
esophageal carcinoma (1 paper, 2023). A primary or metastatic malignant neoplasm involving the esophagus. "Looking for esophageal carcinoma susceptibility in OMIM, we found listed at #133239 RNF6 and DCC; the latter, according to the STRING database, is linked by experiments/co-expression/co-occurrence to TRIO (5p15.2)(a) and MYO10 (5p15.1)(p)." (PMID 38248360, 2023).
gastric cancer (1 paper, 2020). A primary or metastatic malignant neoplasm involving the stomach. "Therefore, FARP1 and TRIO may involve in gastric cancer cell migration, invasion and poor prognosis in a synergistic manner." (PMID 32029704, 2020).
glioma (1 paper, 2023). A benign or malignant brain and spinal cord tumor that arises from glial cells (astrocytes, oligodendrocytes, ependymal cells). "Compared with the normal samples, except for SLAIN2, the CTTNBP2, KIF18A, NAV1, and TRIO protein expression in glioma was elevated, while SRCIN1 and TTBK2 were decreased." (PMID 36979179, 2023). "Our study found that compared with normal tissues, CTTNBP2, KIF18A, NAV1, SLAIN2, and TRIO were upregulated in glioma, while SRCIN1 and TTBK2 were downregulated." (PMID 36979179, 2023). "TTBK2, NAV1, and CTTNBP2 were considered as protective factors, while SRCIN1, TRIO, KIF18A, and SLAIN2 were risk factors for glioma." (PMID 36979179, 2023). "Moreover, TTBK2, NAV1, and CTTNBP2 were protective factors for glioma, while SRCIN1, TRIO, KIF18A, and SLAIN2 were risk factors." (PMID 36979179, 2023).
Impaired glucose tolerance (1 paper, 2024). An abnormal resistance to glucose, i.e., a reduction in the ability to maintain glucose levels in the blood stream within normal limits following oral or intravenous administration of glucose. "Additionally, KO models of JARID2, TRIO, and ULK3 exhibited homeostasis and metabolism phenotypes, including increased circulating creatine, decreased circulating magnesium, impaired glucose tolerance, and increased circulating cholesterol." (PMID 39526184, 2024).
Leukoencephalopathy (1 paper, 2025). This term describes abnormality of the white matter of the cerebrum resulting from damage to the myelin sheaths of nerve cells. "Several genome-wide association studies (GWAS) have identified single-nucleotide polymorphisms (SNPs) in the following genes: TRIO, PRKG1, ANK1, COL4A2, NTN1, and ASTN2 that were associated with increased risk of MTX-induced neurotoxicity and leukoencephalopathy on imaging in patients with ALL." (PMID 41029358, 2025).
liposarcoma (1 paper, 2014). A usually painless malignant tumor that arises from adipose tissue. "We observed that the two liposarcoma samples harbouring TRIO–TERT fusions display a TERT mRNA expression level ~100-fold higher than measured in samples without such a fusion." (PMID 25204415, 2014). "Although not the focus of this study, we describe here such an example: a recurrent fusion in two dedifferentiated liposarcoma samples (2/38; 5%) encoding the non-kinase portion of TRIO, which results in upregulation of its fusion partner TERT." (PMID 25204415, 2014).
lung fibrosis (1 paper, 2023). "In addition, deficiency of Trio Rho Guanine Nucleotide Exchange Factor (TRIO) in epithelial cells and fibroblasts decreases susceptibility to lung fibrosis." (PMID 38157020, 2023). "Therefore, we concluded that deficiency of TRIO in epithelial cell and fibroblast decreases susceptibility to lung fibrosis." (PMID 38157020, 2023). "Our findings exhibit that TRIOBP is one of the target genes and discovers a novel mechanism that miR-29b blocks pulmonary fibrosis by regulation of TRIOBP and TRIO." (PMID 38157020, 2023). "Transcription factor β-catenin is involved in alveolar epithelial–mesenchymal transition during pulmonary fibrosis, we hypnotized that TRIOBP interacts with TRIO modulating fibrosis through β-catenin signal pathway." (PMID 38157020, 2023). "TRIO is upregulated in IPF lung tissues and experimental pulmonary fibrosis." (PMID 38157020, 2023).
lymphoma (1 paper, 2022). A malignant (clonal) proliferation of B- lymphocytes or T- lymphocytes which involves the lymph nodes, bone marrow and/or extranodal sites. "This included transcript levels of two guanine nucleotide exchange factors (GEFs), TRIO and TIAM1, which we subsequently validated as being up-regulated in Eμ-Myc/RelAT505A lymphomas using qPCR." (PMID 36240067, 2022).
myxoid liposarcoma (1 paper, 2017). A liposarcoma characterized by the presence of round non-lipogenic primitive mesenchymal cells and small signet ring lipoblasts within a myxoid stoma with a branching vascular pattern. "At RNA sequencing, significantly elevated expression, compared to myxoid liposarcomas, was seen for TRIO and AMACR in 5p and of CDK4, HMGA2 and MDM2 in 12q." (PMID 28652867, 2017). "Of the selected target genes, AMACR and TRIO in 5p and CDK4, HMGA2 and MDM2 in 12q showed significantly (p < 0.05) elevated expression in relation to myxoid liposarcomas." (PMID 28652867, 2017).
neuroblastoma (1 paper, 2020). Neuroblastoma (NB) is the most common solid, extracranial childhood tumor. "To determine whether the GEFD1 and spectrin variants affected these processes, we transfected N1E-115 neuroblastoma cells with the different TRIO mutants and quantified neurite outgrowth and lamellipodia formation both along the shaft and at the tip of the neurite." (PMID 32109419, 2020).
Neurodevelopmental delay (1 paper, 2020). "Here, we present the largest phenotypic cohort of individuals who had confirmed pathogenic variants in TRIO and who presented with neurodevelopmental delay." (PMID 32109419, 2020). "With regard to the missense mutations, we have identified the seventh spectrin domain of TRIO as a second mutational hotspot and describe how this gives rise to a distinct phenotype of severe neurodevelopmental delay, macrocephaly, and TRIO-mediated RAC1 hyperactivity." (PMID 32109419, 2020).
parasitemia (1 paper, 2025). "In a mouse challenge model, immunization with TRIO VLPs resulted in a modest reduction in liver parasitemia that was more pronounced in mice that received a lower parasite challenge dose." (PMID 39878467, 2025). "Although TRIO VLPs were shown to be immunogenic and produce long-lasting antibody responses, immunization with these VLPs only resulted in modest reductions in liver parasitemia in mice." (PMID 39878467, 2025).
rheumatoid arthritis (1 paper, 2019). A chronic, systemic autoimmune disorder characterized by inflammation in the synovial membranes and articular surfaces. "It has also been shown that the TRIO gene controls leukocyte trans-endothelial migration during inflammatory conditions and other diseases, such as rheumatoid arthritis." (PMID 31311492, 2019).
tumor (20 papers, 2007 to 2025). "POTEE activates Rac1 in the invadopodium by recruiting TRIO-GEF (triple functional domain protein), and it induces tumor cell proliferation and metastasis in vitro and in vivo." (PMID 38098337, 2023). "In high-grade MFS, it was shown that ITGA10 promotes tumor cell survival through the activation of TRIO-RAC-RICTOR-mTOR signaling, and is thus a potential therapeutic target." (PMID 35053609, 2022). "The tumors were measured 7, 14, 21 and 28 days after the tumor injection, and the tumor volume in the circ-TRIO group was significantly increased compared with that in the pLCDH group." (PMID 36075896, 2022). "Among the genes associated with shorter survival in PPS20, TRIO, LDHA, MAP4K4 and ARNTL2 contribute to cellular motility/invasiveness/tumor aggressiveness and thus can also be contributing to shorter event-free survival." (PMID 32310997, 2020). "Moreover, the tumor weight was increased in the circ-TRIO group." (PMID 36075896, 2022). "ITGA10 transmitted specific signals through TRIO and RICTOR, activating RAC/PAK and AKT/mTOR pathways to promote tumor cell survival." (PMID 40258773, 2025). "Activation of the TRIO–RAC–RICTOR–mTOR signaling by the α10 subunit promotes tumor cell survival, and inhibitors of RAC and mTOR have shown anti-tumor effects in vivo, providing a potential therapeutic strategy for high-risk leiomyosarcoma patients." (PMID 37932738, 2023). "Some abnormally regulated genes in our prognostic signature participated in tumour initiation and development, including NUMB, RSRC2, TMC6, CASP8, TRIO, and COMMD5." (PMID 34772375, 2021). "TRIO, SLC20A1, MAP4K4 and ERRF1 genes which are upregulated in high PPS20 patients, were also shown to be involved in cellular proliferation and/or tumor growth." (PMID 32310997, 2020). "Because the epithelial-mesenchymal transition is essential for the metastatic abilities of tumor cells, the protein levels of epithelial and mesenchymal (EMT) markers were further examined, and we found that the knockdown of circ-TRIO contributed to the inhibition of the EMT process." (PMID 36075896, 2022). "In this research, we found that circ-TRIO was highly expressed in tumor tissues and metastatic TNBC cells and increased in TNBC cells compared with hormone-positive BC cells, indicating that circ-TRIO might play vital roles in the malignant behaviors of TNBC." (PMID 36075896, 2022). "This relapse tumor also harbored a broad amplification in TRIO that was not present in the primary lesion." (PMID 28915622, 2017).